EPOR (erythropoietin receptor)
Diseases named in the same sentence as EPOR in open-access papers (continued):
Sharing a sentence is not in itself a finding about the gene and the disease.
Cerebral ischemia (3 papers, 2012 to 2020). Restriction of arterial blood supply to the brain associated with insufficient oxygenation to support the metabolic requirements of the tissue. "Indeed, EpoR in microvascular/capillary endothelial cells is induced during evolution of cerebral infarct following permanent cerebral ischemia in mice and is further enhanced with EPO treatment." (PMID 22567318, 2012). "Erythropoietin (EPO) and erythropoietin receptor (EPOR) system demonstrated to have a key role during central nervous system embryogenesis, have increased expression during cerebral ischemia, and are still expressed in adult brain." (PMID 24490083, 2013).
chronic mountain sickness (3 papers, 2017 to 2023). A pathological condition resulting from chronic exposure to hypoxia at high altitude. "Indeed, we detected decreased expression of EPOR (a downstream target of HIF-1) following CSNK2B KD, suggesting that, in addition to GATA1, HIF signaling might be another potential mechanism underlying the role of CSNK2B in excessive erythropoiesis in Monge’s disease." (PMID 37022795, 2023). "Although expression of hypoxia-inducible factor 1α (HIF-1α) and EPOR does not differ between chronic mountain sickness patients and control subjects, the expression of HIF-2α and EPO is higher in the bone marrow cells of chronic mountain sickness patients than in controls." (PMID 28703764, 2017).
colitis (3 papers, 2012 to 2025). Inflammation of the colon. "TNBS-colitis causes a substantial decrease in colonic EPO mRNA levels whereas splenic EPOR expression is significantly down-regulated in response to systemic Salmonella infection." (PMID 22094132, 2012). "Interestingly, however, another study found that activating the heteromer receptor formed by CD131 and erythropoietin receptor could exert potent anti-inflammatory effects and thus ameliorate experimental colitis in mice." (PMID 40586774, 2025). "While EPOR expression in the colon is not affected by chemically induced colitis, colonic inflammation results in a significant reduction of local EPO mRNA production." (PMID 22094132, 2012). "Expression levels of EPOR mRNA have not only been investigated in tissue macrophages derived from different organs but also in CD11c+ splenic DCs and CD11c+, CD4+ and CD8+ cells isolated from colonic lamina propria of mice suffering from experimental colitis." (PMID 22094132, 2012).
colon carcinoma (3 papers, 2005 to 2016). "Thus, in EpoR-positive colon cancer cell line, administration of agonist caused an increase in active receptor levels." (PMID 27543111, 2016). "We found that EpoR is constitutively expressed in colon cancer cells, although its expression is dependent on cell line type." (PMID 27543111, 2016). "We identified that Epo through EpoR activates Akt, which promotes colon cancer cell growth and proliferation." (PMID 27543111, 2016). "Erythropoietin has been reported to stimulate tumor growth in EpoR-expressing tumors such as breast, cervical, endometrial, gastric, and colon cancer." (PMID 27543111, 2016). "EpoR expression in colon cancer cells increased in parallel with malignancy grade and was highly correlated with the range of angiogenesis." (PMID 27543111, 2016). "However, all of the normal colon samples and 27 (64%) colon tumors expressed detectable EPOR mRNA and all samples expressed detectable ERBB2." (PMID 21318160, 2010). "Due to limited availability of live primary cells from recessions or biopsies, we investigated EpoR expression on DLD-1 and Ht-29 colon cancer cell lines." (PMID 27543111, 2016). "The effect of rEpo on R3230 rat mammary adenocarcinomas, CT-26 mouse colon carcinomas, HCT-116 human colon carcinomas, and FaDu human head and neck tumours, all of which express EpoR, was examined." (PMID 16288305, 2005).
familial erythrocytosis (3 papers, 2018 to 2022). "Primary polycythemia occurs due to somatic and germline mutations in erythroid, granulocytic and megakaryocytic progenitors with hypersensitive erythropoietin receptors (EPOR), leading to their clonal myeloproliferation with plasma erythropoietin (EPO) level below or in the normal range." (PMID 29534684, 2018). "A review of the literature on recently reported mutations in patients with non-MPN erythrocytosis, highlighted the role of some known genes associated with familial erythrocytosis, such as EPO, HBB, VHL EGLN1, EPAS1, and EPOR." (PMID 36290845, 2022).
lymphoma (3 papers, 2008 to 2013). A malignant (clonal) proliferation of B- lymphocytes or T- lymphocytes which involves the lymph nodes, bone marrow and/or extranodal sites. "In contrast, 3/6 (50%) normal lymph node and spleen samples and 10/42 (24%) lymphoma samples expressed detectable EPOR mRNA." (PMID 21318160, 2010). "Interestingly, a statistically significant (P<0.05) decrease in levels of EPOR transcripts in kidney tumours, lung squamous cell carcinoma, lymphomas, and prostate adenocarcinoma relative to normal tissues was identified." (PMID 18349818, 2008).
Mammary Adenocarcinoma (3 papers, 2005 to 2023). "We demonstrate for the first time robust 233 DEGs evoked by human EPOR overexpression in rat mammary adenocarcinoma RAMA 37-28 cells." (PMID 37239828, 2023). "Administration of anti-Epo-antibody, soluble EpoR or an inhibitor of JAK2 resulted in a delay in tumor growth in a experimental model with rat mammary adenocarcinoma cells." (PMID 26919105, 2016).
renal fibrosis (3 papers, 2020 to 2024). A final common manifestation of a wide variety of chronic kidney diseases characterized by glomerulosclerosis and tubulointerstitial fibrosis. "However, persistent high expression of renal EPOR resulted in aggravated renal fibrosis at the chronic stage of kidney IR injury." (PMID 39584501, 2024).
Splenomegaly (3 papers, 2019 to 2022). Abnormal increased size of the spleen. "Co-infection of adult mice with these two viruses leads to splenomegaly due to a polyclonal proliferation of erythroid precursor cells induced by the binding of the truncated envelope protein of SFFV to erythropoietin receptor (EpoR) on erythroid cells." (PMID 30744065, 2019). "The fact that disease development was delayed rather than abrogated and that mice developed severe splenomegaly and high infection levels at the later time points hints at slightly impaired efficiency of SFFV replication or of SFFV gp55 interaction with EpoR or sf-Stk." (PMID 36527061, 2022).
Thrombocytosis (3 papers, 2019 to 2025). Increased numbers of platelets in the peripheral blood. "In cases of familial MPN exhibiting hereditary thrombocytosis and triple-negative MPN, it is proposed that the inherited JAK2 mutations signal through TPOR rather than EPOR." (PMID 31618985, 2019). "Differential signaling of STATs might induce differential clinical phenotypes, such as thrombocytosis being induced by TPOR/STAT1 signaling and erythrocytosis by EPOR/STAT5." (PMID 31618985, 2019).
Alzheimer disease (2 papers, 2013). A progressive, neurodegenerative disease characterized by loss of function and death of nerve cells in several areas of the brain leading to loss of cognitive function such as memory and language. "Erythropoietin treatment also increased the hippocampal response during picture encoding and retrieval in human and increased expression of the EpoR has been found in postmortem analyses of patients with Alzheimers disease." (PMID 23497299, 2013). "Comparison of APP/PS1 and age-matched WT control mice revealed a stronger expression of EPOR but a weaker one of EPO in the Alzheimer’s disease (AD) model mice." (PMID 24124607, 2013).
atherosclerosis (2 papers, 2020 to 2022). A disease characterized by the build-up of fatty material and calcium deposition in the arterial wall resulting in partial or complete occlusion of the arterial lumen. "To investigate whether selective erythroid Jak2VF expression promotes atherosclerosis, we developed hyperlipidemic erythropoietin receptor Cre mice that express Jak2VF in the erythroid lineage (VFEpoR mice)." (PMID 35587375, 2022). "Studies evaluating the effect of rEPO or an EPO derivative ARA290 have shown that rEPO inhibits macrophage activation while promoting phagocytic activity through activation of the EPOR/βcR heterodimer in experimental models of atherosclerosis and autoimmune neuritis." (PMID 32184703, 2020).
cholangiocarcinoma (2 papers, 2013 to 2023). A carcinoma that arises from the intrahepatic biliary tree (intrahepatic cholangiocarcinoma) or from the junction, or adjacent to the junction, of the right and left hepatic ducts (hilar cholangiocarcinoma). "A progressive increase of EPO and EpoR mRNA can already be observed in cholangiocarcinoma." (PMID 36817485, 2023). "An analysis of the EPO/EpoR axis was also performed on human cholangiocarcinoma (CC) cell lines." (PMID 23052842, 2013).
chorioamnionitis (2 papers, 2018 to 2023). A morphologic finding indicating inflammation of the fetal sac membranes. "Altogether, the considerable changes in EPOR expression within the fetal brain in the course of inflammation stresses the need for biomarkers to determine the onset of intra-amniotic infections." (PMID 29673373, 2018). "Specifically, we predicted that EPO, EPOR, MLTR1, SIRT1, HIF1α and HIF2α alterations after chorioamnionitis (CHORIO) would reflect relative changes observed in human preterm infants." (PMID 37546540, 2023).
choroidal neovascularization (2 papers, 2018 to 2022). An eye disorder described by the growth of new blood vessels that originate from the choroid through a break in the Bruch membrane into the sub–retinal pigment epithelium (sub-RPE) or subretinal space. "To test the role of EPO signaling, we used human EPOR knock-in mice with the mWtEPOR gene replaced by either the human EPOR gene (hWtEPOR) or a mutated human EPOR gene (hMtEPOR) in a laser-induced choroidal neovascularization (LCNV) model." (PMID 29391474, 2018). "We wished to investigate the role of EPO in choroidal neovascularization (CNV), a feature of neovascular AMD, and proposed the hypothesis that EPOR signaling affects choroidal macrophages causing them to facilitate the development of CNV through increased cytokine expression." (PMID 29391474, 2018).
Chronic Heart Failure (2 papers, 2023 to 2024). "This prospective randomized controlled study aimed to investigate the effects of switching from a continuous erythropoietin receptor activator (CERA) to one of four HIF-PH inhibitors in patients with chronic heart failure and renal anemia." (PMID 38792306, 2024).
Cognitive impairment (2 papers, 2013 to 2023). Abnormal cognition is characterized by deficits in thinking, reasoning, or remembering. "The clinical relevance of our data showing a prominent increase in overall expression of EPOR in the brains of APP/PS1 mice is reflected by the studies showing increased EPOR in hippocampal and cortical astrocytes in patients with mild cognitive impairment and sporadic AD." (PMID 24124607, 2013). "Amelioration of cognitive impairment by up-regulating the CaMKIIα/CREB/BDNF pathway and EPO/EPOR pathways." (PMID 36875644, 2023).
colorectal cancer (2 papers, 2016 to 2026). A primary or metastatic malignant neoplasm that affects the colon or rectum. "This study aimed to investigate SOCS6 expression and elucidate its association with EPOR in colorectal cancer." (PMID 41514679, 2026). "Erythropoietin Receptor (EPOR) plays a significant role in promoting tumour proliferation and angiogenesis in colorectal cancer (CRC)." (PMID 41514679, 2026). "Recent developments in targeted delivery systems, including platforms based on nanoparticles or siRNA, have opened up new possibilities for the precise manipulation of SOCS6 or EPOR in colorectal cancer." (PMID 41514679, 2026). "EPOR knockdown is a key approach to investigate erythropoietin signalling in colorectal cancer development and its potential interaction with SOCS6." (PMID 41514679, 2026). "There was a complicated, line-specific, biphasic response to EPOR knockdown in colorectal cancer cells during our inquiry into the role of EPOR in cell viability; this contradicts the traditional understanding of EPOR as a straightforward pro-survival protein." (PMID 41514679, 2026). "This study aims to understand the molecular mechanisms that regulate the involvement of SOCS6 in the pathogenesis of colorectal cancer through in vitro cell models, and to investigate its regulatory interaction with EPOR expression following gene knockdown." (PMID 41514679, 2026). "SOCS6 and EPOR exhibit a cell line–specific, bidirectional regulatory relationship in colorectal cancer." (PMID 41514679, 2026). "For better understanding the molecular interaction of SOCS6/EPOR signalling and to evaluate its therapeutic potential in colorectal cancer, future research should incorporate in vivo models, patient samples and proteomic analysis." (PMID 41514679, 2026). "These residues may act as SOCS6 docking sites indicating a possible interaction for the negative regulation mediated by SOCS6 for the EPOR signalling in colorectal cancer cells." (PMID 41514679, 2026). "This research highlights the complex relationship between SOCS6 and EPOR in colorectal cancer and suggests that targeting their interaction may offer new, personalized treatment strategies in colorectal cancer." (PMID 41514679, 2026). "Nevertheless, including both cell lines provides a broader perspective on the functional effects of SOCS6 and EPOR across colorectal cancer phenotypes, highlighting context-dependent regulatory mechanisms that may reflect tumour heterogeneity in vivo." (PMID 41514679, 2026). "It is worth conducting additional mechanistic research to understand the relationships between EPOR and SOCS6 in different forms of colorectal cancer." (PMID 41514679, 2026). "HT-29 and COLO 320DM colorectal cancer cells were transfected with SOCS6 siRNA followed by measurement of SOCS6 and EPOR expression levels by qRT-PCR." (PMID 41514679, 2026).
infarction (2 papers, 2018 to 2021). A localised pathological necrosis of tissue resulting from obstruction of the blood supply usually by a thrombus, an embolus, or vascular torsion. "We assessed RBC-EV contribution to post-MI remodeling in EpoR-Cre/mTmG mice 4 wk after ischemia/reperfusion/infarction (IR)." (PMID 34663679, 2021).
ischemic stroke (2 papers, 2012 to 2017). A stroke disorder caused by obstruction of blood flow to the brain, due to thrombotic (local blood clot formation) or embolic (due to a blood clot or other material traveling from another site) event. "During ischemic stroke, mice that lack EpoR in neural cells show defective neural cell migration to the peri-infarct cortex." (PMID 22567318, 2012). "In mice, EpoR expression increased with ischemic stroke along with increased EPO production, and EPO treatment reduced infarct size, suggesting that in ischemic injury, EpoR increases EPO response and the increase of EPO availability contributes to neuroprotection." (PMID 22567318, 2012). "Our finding of high EPO and EpoR mRNA levels in the brain and our demonstration of the hypoxic upregulation of both of these proteins are suggestive of the mechanisms through which the EA therapeutic modality at GV20 and ST36 may contribute to ischemic stroke." (PMID 28848617, 2017).
lupus (2 papers, 2021). "Moreover, we showed that anti-EPOR antibodies are responsible for the pathological activity of lupus nephritis in systemic lupus erythematosus." (PMID 34059008, 2021). "Subsequently, we identified anti-EPO and anti-EPOR antibodies in the blood of patients with autoimmune diseases, such as CKD accompanied by anemia and systemic lupus erythematosus." (PMID 34059008, 2021). "Mice that lacked EPOR selectively on macrophages developed lupus-like symptoms." (PMID 33796104, 2021).
malaria (2 papers, 2009 to 2020). Malaria is a serious and sometimes fatal disease caused by a parasite that commonly infects a certain type of mosquito which feeds on humans. "EpoR immunolabelling was associated with vessels of varying calibre in 80% (16/20) of the severe malaria brainstem sections." (PMID 19930602, 2009). "Taking all severe malaria cases together, the greatest concordance of EpoR and CD131 occurred with neurons (60% of cases)." (PMID 19930602, 2009). "Epo expression tends to normalize shortly after the onset of hypoxia or traumatic brain injury whereas EpoR can be induced for several days which may explain the observed differences in the incidence of markers in the medulla of the malaria cases." (PMID 19930602, 2009). "CD131 was found on the same vascular elements of small and larger vessels in severe malaria sections as EpoR, but the incidence was much lower (CD131: 30% (6/20) versus EpoR: 80% (16/20))." (PMID 19930602, 2009). "The data, therefore, suggest that EPOR-mediated EPO sensitivity by hepatic erythroblasts precedes EPO production in the liver, and that malaria-induced erythroblastosis in the liver may require hepatic EPO particularly at peak parasitaemia." (PMID 31996238, 2020). "The frequency of EpoR in neuronal cell bodies of severe malaria cases was greater than in non-neurological controls (P = .009)." (PMID 19930602, 2009). "Neurological controls showed consistently high levels of glial labelling for EpoR whereas the severe malaria and non-neurological controls showed a heterogeneous incidence of staining within each group." (PMID 19930602, 2009). "Glial staining of EpoR and CD131 was heterogeneous across cases and discordant in incidence and location in serial sections with only 15% (3/20) of severe malaria cases showing a similar incidence of both markers and one case showing no staining for either marker." (PMID 19930602, 2009). "In severe malaria, there was a greater relative abundance of CD131 compared to EpoR on neurons in CM patients compared with non-CM cases (P = .005)." (PMID 19930602, 2009). "However, EpoR and CD131 labelling of neurons was greater in severe malaria compared with non-neurological controls (P = .009)." (PMID 19930602, 2009).
myeloid leukemia (2 papers, 2016 to 2019). A clonal proliferation of myeloid cells and their precursors in the bone marrow, peripheral blood, and spleen. "The pathways and genes that significantly changed were classified as follows: cancer pathways (EPAS1, CCND1, FGF13), myeloid leukemia pathways (ZBTB16, KIT, IL13), hematopoietic cell lineage pathways (EPOR, GYPA, CD36) and so on." (PMID 27516205, 2016). "In this study, we show that EPO promotes the survival of DA3/EPOR myeloid leukemia cells treated with genotoxic and nongenotoxic agents." (PMID 30622244, 2019).
myeloproliferative disorder (2 papers, 2011 to 2024). A clonal hematopoietic stem cell disorder, characterized by proliferation in the bone marrow of one or more of the myeloid (i.e., granulocytic, erythroid, megakaryocytic, and mast cell) lineages. "The activated Jak2-V617F mutant is present in most cases of BCR/ABL-negative myeloproliferative neoplasms and constitutively activates downstream signals from homodimeric cytokine receptors, such as the erythropoietin receptor (EpoR)." (PMID 22087308, 2011).
oral cancer (2 papers, 2012 to 2024). "Our findings are consistent with several reports showing that patients with oral cancer who had a high levels of EPOR expression had a poor 5-year overall survival rate." (PMID 22639817, 2012). "The results showed that EPOR expression was higher in the tumor tissue than in the adjacent non-tumor tissue in all four samples, indicating that EPOR expression is low in adjacent non-tumor oral tissues and elevated in oral cancer tissues." (PMID 22639817, 2012).
Ovarian Tumor (2 papers, 2001 to 2015). "RT-PCR analysis demonstrated the expression of mRNAs for Epo and EpoR in the transplants of uterine and ovarian tumours in nude mice." (PMID 11259101, 2001).